ANXA1 (annexin A1)
Diseases named in the same sentence as ANXA1 in open-access papers (continued):
Sharing a sentence is not in itself a finding about the gene and the disease.
cancer (continued). "The available epidemiological studies have shown that elevated levels of ANXA1 correlate with poor prognosis and advanced disease stages in these cancers." (PMID 38892394, 2024). "The overexpression of ANXA1 by cancer cells has been demonstrated to increase cell proliferation, angiogenesis, migration/ invasion and drug resistance." (PMID 38200229, 2024). "In contrast, some studies have found downregulation of ANXA1 expression in cancers such as cervical and thyroid." (PMID 38200229, 2024). "Annexin 1 (ANXA1) is a protein member of the annexin family with multifunctional roles in cancer development and progression." (PMID 38397187, 2024). "Whilst this study successfully demonstrated MDX-124 has the potential to impact on ANXA1 overexpressing cancers, there were some limitations." (PMID 38200229, 2024). "Many proteins identified in exosomes including lactate dehydrogenase A (LDHA), annexin A1/2 (ANXA1/2), or HSP90, are known to be mutated in multiple cancer types." (PMID 38200509, 2024). "Expression of the annexin family had beenstudied in a wide range of cancers, including ANXA1, ANXA2 and ANXA13 Annexin familymembers were involved in signal transduction, cellular differentiation,proliferation and thus in tumorigenesis (Lizarbe etal., 2013)." (PMID 38626574, 2024). "Imaging flow cytometry was used to determine the level of expression and cellular localisation of ANXA1 in representative cancer cell lines." (PMID 38200229, 2024). "MiR-196a promoted cancer progression via ANXA1 and CCL2, however, blocking CCL2 restricted invasion within spheroids." (PMID 38455762, 2024). "In contrast, significantly higher signals in flotillin-1 and annexin A1 were detected in m/lEVs derived from cancer cells assessed relative to sEVs." (PMID 36992223, 2023). "ANXA1 is synthesized by immune, epithelial, and cancer cells via the action of different chemical mediators, such as glucocorticoids and cytokines." (PMID 37373303, 2023). "In ICD, after plasma membrane permeabilization, the liberation of ANXA1 guides DC to migrate to the proximity of dying cancer cells via a formyl peptide receptor 1 (FPR1)-dependent mechanism." (PMID 36949244, 2023). "Annexin A1’s role in cancer includes regulation of cellular proliferation, metastasis, lymphatic invasion, development of resistance to anti-cancer treatment, and modulation of cancer-related signalling pathways." (PMID 37833989, 2023). "ANXA1 is an immune-modulating protein with diverse functions in immune system, cancer, central and peripheral inflammation." (PMID 37507468, 2023). "Immune infiltration, fibrosis, and cancer-related processes were markedly enriched in PSC with high expression of ANXA1." (PMID 37735492, 2023). "Extracellular ANXA1 promotes stem cell differentiation 50 and reduces cancer cell growth and aggressiveness." (PMID 36632451, 2023). "It has been reported that F. nucleatum and Annexin A1 cause chemo-resistance metastasis and poor prognosis in CRC; therefore, Annexin 1 can be considered a biomarker for all cancers in which F. nucleatum is present." (PMID 37764202, 2023). "Plenty of studies have confirmed that expression level of ANXA1 protein is related with the invasiveness of various cancer types." (PMID 37434432, 2023). "Annexin A1 is a calcium-dependent phospholipid-binding protein that plays a variety of roles in the immune system and cancer." (PMID 36077674, 2022). "This can be seen in diseases such as cancer, where the role ANXA1 plays can depend on the signalling pathways that it is involved in, as well as the localization of the molecule." (PMID 35146757, 2022). "Further in‐depth studies revealed that ANXA1 is deregulated in a large number of cancers and is involved in multiple cancer processes, including cell proliferation, invasion, metastasis and radiosensitivity." (PMID 35770335, 2022).
cancer (continued). "Our further functional ANXA1 data suggested that ANXA1 promoted GBM cell proliferation, migration and invasion; these functions are consistent with ANXA1 functions in many other cancers." (PMID 35770335, 2022). "Processes associated with ICD result in the emission of DAMPs, such as HSP70, HSP90, calreticulin, HMGB1, ATP, type I IFN, cancer cell-derived nucleic acids, ANXA1, and others." (PMID 36015189, 2022). "These genes, such as ANXA1, SMC2, KIF23, and DDX5, are primarily associated with cancer cell proliferation, metastasis, and poor prognosis." (PMID 35184675, 2022). "ANXA1 has the role of the homing factor to recruit DCs or their precursors to cancer cells undergoing ICD, through binding to its receptor formyl peptide receptor 1 (FPR1)." (PMID 36429101, 2022). "This indicates that microglia migration is indeed dependent on exogenous ANXA1 secreted from cancer cells." (PMID 35382852, 2022). "We rechecked the RNA-seq data of YTHDC1 and found that Annexin-A1 (ANXA1) was upregulated after knockdown of YTHDC1 in cancer cells." (PMID 35974388, 2022). "Immunostimulatory danger-associated molecular patterns (DAMPs) (such as ANXA1, CALR, and HMGB1) and cytokines (such as IFN and CXCL10) were used to evaluate the immunogenicity of cancer cell death." (PMID 36003383, 2022). "In the 178 PC patients, the LAMB3, FN1, KRT17, KRT19, and ANXA1 were also upregulated in cancer tissue, compared with adjacent tissues and normal tissues." (PMID 35428170, 2022). "To gain insight into the molecular mechanism of ANXA1 as a cancer promoting factor, we conducted in-depth analyses of the TCGA dataset." (PMID 34991599, 2022). "Abnormal expression and dysfunction of Annexins (ANXA1-11, 13) have been widely found in several types of cancer." (PMID 35205125, 2022). "Annexin‐1 (ANXA1) is widely reported to be deregulated in various cancers and is involved in tumorigenesis." (PMID 35770335, 2022). "These multiple functions make ANXA1 an important target within many cancers and emphasize the need for increased understanding of the exact mechanisms of ANXA1‐mediated cellular activation." (PMID 35146757, 2022). "For instance, annexin A1 (ANXA1) proteins are cargo molecules in cancer cell-derived exosomes and activate epithelial–mesenchymal transition (EMT) in exosome-receiving cancer cells." (PMID 35055115, 2022). "A recent study showed that ANXA1 is associated with NEMO or RIP1, which regulates NF-κB signaling in cancer cells." (PMID 35604142, 2022). "Accumulating years of studies have shown the anti‐inflammatory activities of ANXA1 in several cancers." (PMID 35770335, 2022). "For instance, in prostate or oesophageal cancers, a downregulation of this protein has been observed, whereas in hepatocellular as well as colorectal cancers annexin A1 elevated expression has been detected." (PMID 34444893, 2021). "We further screened the activated ligand-receptor pairs between ductal cells and these two stroma-cell types and defined several cancer-associated pairs, such as EGFR/TGFB1, ANXA1/FPR3, EREG/EGFR, and ICAM1/AREG." (PMID 34326696, 2021). "The de-regulated signaling pathways in cancers triggered by extra- or intracellular AnxA1 activities have yet to be fully elucidated." (PMID 33810523, 2021). "AnxA1 has been described as an essential player in several aspects of cancer, such as proliferation, chemoresistance, invasion, and metastasis formation." (PMID 34208346, 2021). "Although numerous publications demonstrate that ANXA1 plays multifaceted roles in cancer development and progression, its expression and function appear to be “cancer type-specific”." (PMID 33804148, 2021). "Although Annexin A1 has been extensively studied for its anti-inflammatory activity, it has been shown that, in the cancer context, its activity switches from anti-inflammatory to pro-inflammatory." (PMID 34571894, 2021).
cancer (continued). "Among them, ANXA1 was highly expressed in various malignant tumors, and upregulation of ANXA1 levels in the serum was related to the pathological grade and clinical stage of patients with particular forms of LUAD." (PMID 34350210, 2021). "Collectively, the information presented in this section emphasizes the essential role of AnxA1 and its signaling pathway through FPRs in the aggressiveness of several cancers." (PMID 34571894, 2021). "Here, we show that the complex ANXA1/EVs modulates the macrophage polarization further contributing to cancer progression." (PMID 34681678, 2021). "ANXA1 has also been shown to affect the sensitivity of cancer cells to various chemotherapeutic drugs." (PMID 34912807, 2021). "Investigations into the roles and mechanisms of AnxA1 in various disease models in inflammation and cancer would further clarify the protein’s involvement in pathophysiology." (PMID 34944032, 2021). "ANXA1 preserves the cytoskeleton integrity and plays a significant role in the malignant phenotypes of cancer cells in vitro." (PMID 33804148, 2021). "As observed from previous reports of ANXA1 in different cancers, we also revealed that ANXA1 was mainly involved in immune-related functions, such as interferon-gamma response and regulation of innate immune response." (PMID 34912807, 2021). "A protein that has attracted much attention, for its immunomodulatory functions in cancer, is the phospholipid and calcium-binding protein, Annexin A1." (PMID 34571894, 2021). "The decrease in IL-12 correlates with cancer progression and metastasis and is probably dependent on the upregulation of IL-10 induced by AnxA1." (PMID 34571894, 2021). "In cancer, Annexin A1 function depends on its subcellular localization: roles for nuclear, cytoplasmic, membrane-associated, free extracellular, and microvesicle encapsulated forms have been described." (PMID 33800279, 2021). "ANXA1 activation was reported to play a critical role in the EMT pathway in several types of cancer, including PC, consistent with our results." (PMID 33804148, 2021). "Taken together, these findings point towards an important role of AnxA1 in the induction of immune suppression in the cancer context." (PMID 34571894, 2021). "Annexin A1 (ANXA1) is a calcium-dependent phospholipid-binding protein and has been implicated in multiple functions essential in cancer, including cell proliferation, apoptosis, chemosensitivity, metastasis, and invasion." (PMID 34912807, 2021). "Annexin A1 is an immune-modulating protein with diverse functions, one of which is an “eat me signal,” that plays multiple roles in cancer growth and metastasis." (PMID 34712237, 2021). "AnxA1 present in EVs promotes the activation of keratinocytes through the activation of FPRs in an autocrine loop, which promotes cancer cell motility." (PMID 34208346, 2021). "Cancer of the breast, colorectal, lung, and kidney with a low expression of ANXA1 is scarcely infiltrated by DC and cytotoxic T lymphocytes, supporting the idea that ANXA1 deficiency facilitates immune escape." (PMID 33804148, 2021). "We believe this is because we analyzed the involvement of ANXA1 in cancer progression—the worsening of existing cancer." (PMID 33804148, 2021). "Based on this, the AnxA1/EGFR interaction seems to play a relevant role in immune suppression in the cancer context." (PMID 34571894, 2021). "In the cancer context, it has been shown that AnxA1 promotes the stabilization and the constitutive activation of EGFR, as well as the nuclear localization of this receptor." (PMID 34571894, 2021). "Over the last few years, a lot of studies have explored a variety of therapeutic roles for AnxA1 in cancer." (PMID 33810523, 2021). "During ICD, annexin A1 guides antigen-presenting cells to dying cancer cells while HSP70, HSP90, HMGB1 and other molecules promote uptake and cancer antigen presentation to T cells." (PMID 34579759, 2021).
cancer (continued). "Our study results add another piece of evidence that ANXA1 plays various roles in different cancer types and its complex regulation mechanisms." (PMID 34439260, 2021). "In this type of cancer, the N-terminal peptide of AnxA1 induces a signaling cascade through FPR2 that activates ERK, Akt and NF-kB." (PMID 34571894, 2021). "Given that ANXA1 expression is significantly correlated with cancer cell proliferation, we predicted that ANXA1 high PC is associated with worse survival." (PMID 33804148, 2021). "Extracellular Annexin A1 released from either viable or necrotic cancer cells can bind to and activate G-protein-coupled formyl peptide receptors (FPRs) on neoplastic cells to promote mitogenesis in an autocrine manner." (PMID 33800279, 2021). "In this review, we aim to describe the role of PLA2 in the establishment of TME, focusing on cancer-derived exosomes, and modulatory activities of Annexin A1." (PMID 34208346, 2021). "In this review, we aimed to describe the role of phospholipase A2 (PLA2), and its interaction with the protein Annexin A1 (AnxA1), in cancer development and progression." (PMID 34208346, 2021). "ANXA1 expression has been shown to take part in a wide variety of cancer biology, including carcinogenesis, cell proliferation, invasion, apoptosis, and metastasis, in addition to the initially identified anti-inflammatory effect in experimental settings." (PMID 33804148, 2021). "ANXA1 is known to play a wide variety of functions in cancer biology, including carcinogenesis, cell proliferation, apoptosis, invasion, and metastasis, in addition to an anti-inflammatory effect." (PMID 33804148, 2021). "ANXA1 has been shown to be abnormally expressed in the immune microenvironment of cancer, and antagonizing ANXA1 expression has often achieved good results." (PMID 34422796, 2021). "In this context, some studies are indicating the role of AnxA1 in inducing resistance of cancer cells toward chemotherapies." (PMID 34571894, 2021). "Cluster 1 has the maximum score 32.549, with 52 nodes and 830 edges, including known cancer-related genes, such as ANXA1 (annexin A1) and SSTR2 (somatostatin receptor type 2)." (PMID 34512870, 2021). "Intriguingly, HSPA5 aberrantly expressed in bone-related cancer tissues compared with the normal tissues, whereas ANXA1 expression appeared to be downregulated in cancer." (PMID 33291071, 2020). "Differential expression of Annexin A1 is shown to play a role in cellular proliferation, metastasis, lymphatic invasion, and development of resistance to anti-cancer treatment." (PMID 32823805, 2020). "Annexin A1 is a Ca2+ binding protein participating in vesicular trafficking as well as membrane organization, and thus to regulate cancer progression." (PMID 32215176, 2020). "ANXA1 is an endogenous inhibitor of NF-κB that can be induced in cancer cells and experimental tumors by potent anti-inflammatory glucocorticoids and modified nonsteroidal anti-inflammatory drugs." (PMID 32887260, 2020). "In recent years, there has been an exponential interest in the role of Annexin A1 (Anx-A1) in cancer due to the increasing number of studies investigating the effect of this endogenous protein in different types of cancer." (PMID 32823805, 2020). "A wide range of cells secretes AnxA1, including those of the innate immune system, as well as epithelial and cancer cells." (PMID 32403233, 2020). "AnxA1 mediates physiological processes in the body although its secretion is highly augmented during challenging processes, such as inflammation and cancer." (PMID 32403233, 2020). "ANXA1 can stimulate migration, invasion and metastasis of cancer cells, possibly due to the cytoskeletal remodeling and the activation of signaling pathway related to formyl peptide receptors." (PMID 32756339, 2020). "It has been observed that the secreted form of ANXA1 stimulates a more aggressive phenotype in cancer cells by its interaction with FPRs." (PMID 33353163, 2020).
cancer (continued). "A related family member protein anxA2 has a high degree of sequence homology to anxA1 (55%), is upregulated in cancer, and is known to be expressed on endothelium; therefore binding to anxA2 was assessed to ensure antibody specificity." (PMID 32497150, 2020). "In this study, overexpression of ANXA1 in the PBMCs of cancer patients, depending on the cancer proliferation status, suggests the potency of ANXA1 as a biomarker of the identification of cancer." (PMID 32226026, 2020). "The proliferation decrease found in this study is corroborated by refs 26, 27, which also observed this phenomenon in cancer cell lines after treatment with ANXA1." (PMID 30984541, 2019). "Within the tumors, the ANXA1 expression was mainly detected in the cytoplasm of cancer cells, stromal cells, and myoepithelial cells." (PMID 31461932, 2019). "While ATP, CRT, and HMGB1 represent the classical hallmarks of immunogenic cell death, other molecules behave as DAMPs, for instance annexin A1 (ANXA1) and cancer cell-derived nucleic acid." (PMID 31440242, 2019). "Taken together, these results indicated that ANXA1 contributed to HDS-induced growth stimulation in cancer cell clusters by activating the PI3K/AKT pathway." (PMID 31882967, 2019). "We found that approximately two-thirds of annexin A1 in the TME comes from cancer cells, whereas the remaining one-third is contributed from the host." (PMID 31545917, 2019). "To gain a functional insight on annexin A1 biology in the context of cancer, we performed a stable knockdown of this molecule using shRNA lentiviral transfection." (PMID 31545917, 2019). "Findings presented here suggest the importance of annexin A1 in altering migration of cancer cells as well as their proliferation, both in culture and as subcutaneous xenografts." (PMID 31545917, 2019). "Transfected cancer cells reached ~80–85% inhibition of Anxa1 mRNA production, as assessed by two different primer pairs." (PMID 31545917, 2019). "We focused our analysis on five of the eight overlapping genes because their function is deregulated in cancer and/or AD, as in the case of ANXA1." (PMID 31749682, 2019). "AnxA1 actions on cell proliferation are controversial, as both pro- and anti-proliferative actions have been described in different types of cancers and inflammatory cells." (PMID 30250432, 2018). "A protein related to invasive phenotype (E-FABP) and a potential cancer marker showing an unanticipated expression profile (annexin A1) were selected for validation by Western blotting and/or immunohistochemical assay." (PMID 30157864, 2018). "Second, S100A11 and ANXA1 proteins have recently been shown to protect against cell membrane damage and promote survival of cancer cells." (PMID 29844306, 2018). "The secretion of annexin A1 (ANXA1) helps guide the APCs to the dying cancer cells where they become activated." (PMID 29666625, 2018). "Extracellular ANXA1 has been described to play several roles in the acquisition of a more aggressive phenotype in cancer cells, for example as a modulator of EMT-like phenotypic switch." (PMID 30518142, 2018). "As predicted by the inteGREAT pan-cancer analysis, ANXA1 exhibited significantly higher expression in the two basal cell lines HCC1599 and MB-157." (PMID 29971090, 2018). "Annexin A1 (ANXA1) is a 37 kDa Ca2+-regulated phospholipid-binding protein that is involved in a wide range of physio-pathological processes, including cancer development." (PMID 29986379, 2018). "miR-196a showed a significant inverse correlation with annexin A1 mRNA levels in 12 cancer cell lines of oesophageal, breast, and endometrial origin, identifying miR-196a as the candidate miRNA targeting annexin A1." (PMID 29462943, 2018). "Particularly, the extracellular form of ANXA1 plays an important role in cancer cell migration, invasion and metastasis." (PMID 30518142, 2018). "Understanding the molecular mechanisms of ANXA1 in cancer also involves the investigation of its relationship with miRNAs." (PMID 29986379, 2018).